GATA1 (GATA binding protein 1)
Diseases named in the same sentence as GATA1 in open-access papers (continued):
Sharing a sentence is not in itself a finding about the gene and the disease.
breast carcinoma (continued). "Taken together, these data indicate that GATA1 regulates breast cancer cell growth and tumor angiogenesis through SET7." (PMID 26848522, 2016). "In this study, we uncovered a novel function of GATA1 in regulating tumor angiogenesis and breast cancer cell growth in vitro and in vivo." (PMID 26848522, 2016). "Here, we showed that GATA1 binds to the GATC sequence (−2 to +2 bp) containing the transcription start site (TSS) to enhance the transcription of VEGF in breast cancer cells." (PMID 26848522, 2016). "We confirmed the specificity of the antibodies for GATA1 and SET7 used in IHC by antigen competition and immunoblotting of lysates from MCF7 and ZR75-1 breast cancer cells transfected with GATA1 and SET7 siRNA." (PMID 26848522, 2016). "We coupled GATA1 phosphorylation to histone deacetylation in E-cadherin transcription regulation in breast cancer cells." (PMID 25726523, 2015). "In breast cancer aggressiveness, GATA1 is identified as a key feature by enhancing survivin expression." (PMID 25726523, 2015). "Our result, therefore, indicate that phosphor-Ser161/Ser187 is a novel regulatory mechanism by which GATA1 promotes breast cancer cell migration and invasion." (PMID 25726523, 2015). "GATA1 binds to E-cadherin promoter, down-regulates E-cadherin expression, disrupts intercellular junction and promotes metastasis of breast cancer cell in vivo." (PMID 25726523, 2015). "The high expression rate of the PAK5 and GATA1 were 66.25% (53/80) and 62.50% (50/80) in breast cancer tissues and low expression rate 33.75% (27/80) and 37.50% (30/80) in matched adjacent noncancerous tissues." (PMID 25726523, 2015). "EMSA and ChIP assays confirmed that C/EBP, GATA1 and Stat3 bind to Jab1 promoter in breast carcinoma cells." (PMID 21689417, 2011). "Jab1 promoter analysis led to the identification of C/EBP-β, GATA-1, and Stat3 as positive regulators of Jab1 transcription in breast cancer cells." (PMID 21689417, 2011). "Furthermore, it was shown that GATA1 promotes breast cancer growth and metastasis by regulating VEGF expression." (PMID 39684309, 2024). "GATA1 or GATA-binding factor 1 promote the EMT in breast cancer." (PMID 35267457, 2022). "Two previous studies found that GATA1 and its phosphorylation may play an important role in the metastasis of breast cancer, and GATA1 can be used as an independent prognostic marker for breast cancer." (PMID 35488350, 2022). "In breast cancer, GATA1 is overexpressed and promotes survivin expression." (PMID 31093285, 2019). "Furthermore, GATA1 enhanced breast cancer cells invasion and angiogenesis through promoting epithelial-mesenchymal transition (EMT) and VEGF expression." (PMID 31093285, 2019). "PAK5-mediated GATA-1 phosphorylation regulates EMT in breast cancer cells." (PMID 31783675, 2019). "The conditioned medium from GATA1 knockdown breast cancer cells inhibited HUVEC tube formation." (PMID 26848522, 2016). "Importantly, Neutralization of cancer cell-secreted VEGF by a VEGF neutralizing antibody abolished the ability of the conditioned medium from GATA1-overexpressing breast cancer cells to promote the formation of new blood vessels on the CAM." (PMID 26848522, 2016). "Recently, GATA1 has been shown to be overexpressed in breast carcinomas." (PMID 26848522, 2016). "We further showed that, in breast cancer, GATA1 expression positively associates with tumor size, nodal status, grade, and GATA1 is an independent poor prognostic factor." (PMID 26848522, 2016). "Moreover, VEGFR2 knockdown in HUVEC cells abolished the ability of the conditioned medium from GATA1- or SET7-overexpreesing breast cancer cells to stimulate vascular tube formation." (PMID 26848522, 2016). "Since down-regulation of E-cadherin expression plays an essential role in tumor aggressiveness, these data indicate that GATA1 may play a critical role in breast cancer metastasis, although further data should be provided." (PMID 25726523, 2015).
breast carcinoma (continued). "Importantly, the high level of PAK5 expression correlated with the expression of GATA1 in breast cancer tissues (p = 0.033)." (PMID 25726523, 2015). "It is recently reported that GATA1 is overexpressed in breast carcinomas." (PMID 25726523, 2015). "Our findings provide insights into the novel function of GATA1, contributing to a better understanding of the EMT, indicating that GATA1 and its phosphorylation may play an important role in the metastasis of breast cancer." (PMID 25726523, 2015). "In addition, we have evidence that GATA1 disrupts cell-cell junction and promotes the migration of breast cancer cells." (PMID 25726523, 2015). "We also detected higher GATA-1 expression in the breast cancer cells compared with normal mammary epithelial cells and taken together could be a driving force in leading Jab1 expression in breast cancer." (PMID 21689417, 2011). "Our data indicate that GATA1 and its phosphorylation may play a critical role in the metastasis of breast cancer, which might open up new potential therapeutic avenues for the treatment of breast cancer." (PMID 25726523, 2015). "These include EMT (TWIST1, SNAIL1, RUNX1, RUNX2, HIF1, and NOTCH1), breast cancer maintenance (OCT4, SP1, GATA1, ATF1, FOXO3a, ELK1, VDR, and NRF1), pro-metastatic responses (SMAD2/3, HNF1a, GLI1, NANOG, YY1, MYB1, and AP1), and immune modulation (STAT1/3)." (PMID 38398186, 2024). "We have previously demonstrated that GATA1 promotes breast cancer growth and metastasis through regulating VEGF expression, but the role of GATA1 in PDAC remains unexplored." (PMID 31093285, 2019). "More recent studies have revealed that GATA1 and GATA2 also participate in the progression of breast cancer and prostate cancer via EMT processes." (PMID 30872657, 2019). "We further confirmed GATA1 overexpression-mediated enhancement of VEGF-Luc reporter activity using our GATA1 expression construct in ZR75-1, MCF-7 and MDA-MB-231 breast cancer cells." (PMID 26848522, 2016). "Expression of both GATA1 and SET7 positively correlated with VEGF expression in 80 human breast cancer tissues (P = 0.004 and P = 0.005, respectively)." (PMID 26848522, 2016). "Immunohistochemical staining showed that expression of GATA1 and SET7 was upregulated and positively correlated with VEGF expression and microvessel number in 80 breast cancer patients." (PMID 26848522, 2016). "SET7 knockdown also abrogated the ability of GATA1 overexpression to enhance proliferation of MCF7 and MDA-MB-231 cells, suggesting that GATA1-mediated breast cancer cell proliferation is dependent on SET7." (PMID 26848522, 2016). "In MCF7 and MDA-MB-231 breast cancer cells, overexpression of GATA1 or SET7 increased the transcription of VEGF, bcl-xL, and Myc, whereas knockdown of GATA1 or SET7 decreased that of VEGF, bcl-xL, and Myc." (PMID 26848522, 2016). "However, the function of GATA1 in breast cancer metastasis remains unclear." (PMID 25726523, 2015). "Meanwhile, we showed that phosphorylated GATA1 by PAK5 recruits more HDAC3/4 to promote transcriptional repression of E-cadherin, leading to the EMT of breast cancer cells." (PMID 25726523, 2015). "It has been reported that GATA1 is overexpressed in aggressive breast cancer and GATA3, another GATA family member, inhibits breast cancer metastasis through increasing E-cadherin expression." (PMID 25726523, 2015). "Based on these results, we propose that the phosphorylated GATA1 by PAK5 recruits more HDAC3/4 to the E-cadherin promoter, thus promotes transcriptional repression of E-cadherin, leading to the EMT of breast cancer cells." (PMID 25726523, 2015). "Most of these conserved TFBSs involved in breast cancer (e.g., AP-1, NFκB, and STAT5), stem cells and embryonic development (e.g., OCT1, PAX6, GATA1), and therefore had the highest potential for regulating CD44 and for being involved in breast cancer." (PMID 23226410, 2012).
breast carcinoma (continued). "In breast cancer cells, knockdown of SET7/9 not only reduced VEGF promoter activity and decreased VEGF expression at the mRNA level, but also abolished the ability of GATA1 to activate VEGF131." (PMID 35069908, 2022). "Prior reports demonstrated acetylated and phosphorylated GATA-1 influenced gene expression in tumorigenesis, such as breast cancer and hematologic malignancies, but there is no study about GATA-1 in LDAC." (PMID 29100282, 2017). "GATA1 and SET7 are independent poor prognostic factors in breast cancer." (PMID 26848522, 2016). "Consistent with previous study, we also found that GATA1 is overexpressed in breast cancer patients (data not shown)." (PMID 26848522, 2016). "Consistent with previous report, GATA1 was overexpressed in breast cancer patients (data not shown)." (PMID 26848522, 2016). "Moreover, both GATA1 and SET7 promote breast tumor growth and are independent prognostic factors of breast cancer." (PMID 26848522, 2016). "Since both GATA1 and SET7 are overexpressed in breast cancer patients, and GATA1 and SET7 promote not only breast cancer cell growth but also tumor angiogenesis, inhibition of GATA1 and/or SET7 may be a useful strategy for breast cancer therapy." (PMID 26848522, 2016). "PAK5 phosphorylates the transcription factor GATA1 mainly at Ser161 and Ser 187, phosphorylated GATA1 recruits more HDAC3/4 to the promoter of E-cadherin and consequently suppresses the transcription of E-cadherin gene and promotes the EMT of breast cancer cells." (PMID 25726523, 2015). "Further, GATA1 wild type but not GATA1 S161A S187A mutant promoted breast cancer cell invasion in vitro and metastasis in vivo." (PMID 25726523, 2015). "Here, we found that GATA1, as a novel E-cadherin repressor, promotes EMT in breast cancer cells." (PMID 25726523, 2015). "It was reported that GATA1 was overexpressed in breast cancer tissues and we found that there was a negative relationship between the expression of GATA1 and E-cadherin in NMuMG, MCF-7, ZR-75-1 and ZR-75-30 cell lines." (PMID 25726523, 2015). "Transcription factor GATA1 has a critical anti-apoptotic role in breast cancer, but its function for metastasis has not been investigated." (PMID 25726523, 2015). "In human breast cancer, GATA1 as a negative transcriptional regulator binds the Peroxiredoxin 5 (Prx5) gene, and overexpression of Prx5 in mammary tissue is associated with the inhibition of apoptosis and poor prognosis." (PMID 24564526, 2014). "Thus, we speculate that GATA1 might be involved in EMT and the metastasis of breast cancer." (PMID 25726523, 2015). "It has been reported that Akt directly phosphorylated GATA1 at serine 310, and PAK5 was in higher expression in breast cancer tissues than matched adjacent noncancerous tissues." (PMID 25726523, 2015).
myelofibrosis (18 papers, 2016 to 2025). A partial or complete replacement of the bone marrow stroma by fibrous tissue. "In a GATA-1-deficient myelofibrosis model, LOX overexpression drives ECM buildup and marrow fibrosis, which BAPN can mitigate." (PMID 40661776, 2025). "In fact, hypo-morphic GATA1 mutations selectively decrease GATA1 in megakaryocytes and induce myelofibrosis in mice and a bone marrow histology like primary myelofibrosis in humans." (PMID 36871061, 2023). "Previous studies have established that in both MF patients and in MPN driver mutation animal models of myelofibrosis the reduced levels of GATA1 is due to a ribosomopathy that reduces the GATA1 content in the malignant MKs." (PMID 35392239, 2022). "We measured only the total level of Gata1 mRNA because in humans the ribosomopathy induced by the driver mutations found in myelofibrosis equally reduces the megakaryocyte content of the full-length and short isoform of the GATA1 protein." (PMID 34707640, 2021). "Cis-acting regulatory mutations that affect GATA1 expression caused myelofibrosis and acute erythroblastic leukemia in mice." (PMID 34832908, 2021). "The other two are cis-acting regulatory mutations affecting expression of the Gata1 gene, which have been shown to cause acute erythroblastic leukemia and myelofibrosis in mice." (PMID 28119852, 2016). "The causative role exerted by these immature megakaryocytes in the development of myelofibrosis was then confirmed by the observation that the hypomorphic Gata1 mutation, which selectively decreases Gata1 transcription in megakaryocytes, induces myelofibrosis in mice." (PMID 34943811, 2021). "Furthermore, quantitative reduction of GATA1 has been described as causal in acute erythroblastic leukemia and myelofibrosis in mice." (PMID 28119852, 2016). "In patients with myelofibrosis, abnormal immature megakaryocytes in the bone marrow display reduced GATA1 protein expression and secrete a range of pro-inflammatory cytokines (such as IL-1ß, TGF-ß) and growth factors (including b-FGF, PDGF, and VEGF)." (PMID 40507313, 2025). "Reduced GATA-1 expression activates in mice a disorder similar to human primary myelofibrosis, characterized by myelofibrosis, extramedullary hematopoiesis, and anemia." (PMID 34945127, 2021). "These concepts have inspired ongoing clinical trials, which are testing the efficacy of treating myelofibrosis patients with drugs that either increase GATA1 content, restore megakaryocyte maturation, or inhibit TGF-β signaling." (PMID 34943811, 2021). "We suggest that, as hypothesized by the Balduini laboratory, the GATA1 hypomorphic immature megakaryocytes found in the bone marrow of patients with myelofibrosis are niche-poised cells and are directly responsible for fibrosis." (PMID 34943811, 2021). "Whether the megakaryocytes observed by the Balduini laboratory in myelofibrosis are niche-poised cells containing low levels of GATA1 induced by the high levels of transforming growth factor-β (TGF-β) present in the microenvironment has not been established as yet." (PMID 34943811, 2021). "In addition, ribosomopathies affecting the efficiency of translation of GATA1 mRNA are associated, in addition to Diamond Blackfan Anemia, with primary myelofibrosis, the most severe of the Philadelphia-negative myeloproliferative disorders." (PMID 34707640, 2021). "Given the important role of GATA transcriptional regulators in myelofibrosis pathogenesis and in Tet2-mutant AML, we performed quantitative PCR for Gata1 and Gata2 in donor-derived MEPs isolated from vehicle- and inhibitor-treated mice." (PMID 29355841, 2018). "Recently, several biomarkers have been introduced for primary myelofibrosis, such as circulating YKL-40 and GATA-1, but not for SLE-associated myelofibrosis." (PMID 35399432, 2022).
myelofibrosis (continued). "Myelofibrosis (MF) is a progressive chronic myeloproliferative neoplasm characterized by hyperactivation of JAK/STAT signaling and dysregulation of the transcription factor GATA1 in megakaryocytes (MKs)." (PMID 34383713, 2021).
transient myeloproliferative disorder (18 papers, 2015 to 2025). "Detecting trisomy 21 mosaicism and the GATA1 mutation is critical for diagnosing transient myeloproliferative disorder, planning the best treatment and determining prognosis." (PMID 40519552, 2025). "Transient myeloproliferative disorder is a clonal myeloproliferative syndrome that occurs in the presence of mutations in the GATA1 gene and chromosome 21 trisomy." (PMID 40519552, 2025). "Trisomy of chromosome 21 clearly predisposes the development of GATA1 mutations in utero, but little is known regarding risk factors for the development of ML-DS in a subset of individuals with transient leukemia." (PMID 38275407, 2024). "These pathognomonic GATA1 mutations are detectable in all patients with ML-DS, but postnatally acquired secondary mutations are necessary to drive the transformation of transient leukemia to ML-DS." (PMID 38275407, 2024). "Individuals with T21 often have polycythemia and thrombocytopenia, and as infants, are predisposed to a preleukemic transient myeloproliferative disease (TMD) associated with GATA1 mutations." (PMID 33768218, 2020). "The GATA1 mutated HSPCs showed enhanced percentage of immature megakaryoblasts, which is the hallmark of transient leukemia in DS children." (PMID 33102613, 2020). "Pre-leukemic myeloproliferative changes in DS foetal livers precede the acquisition of GATA1 mutations, transient myeloproliferative disorder (DS-TMD) and acute megakaryocytic leukemia (DS-AMKL)." (PMID 25973911, 2015). "Notably, 5% to 10% of children with DS under four years of age are diagnosed with the preleukemic state of transient myeloproliferative disorder (TMD), which is invariably driven by GATA1 mutations generating a protein with a truncated N-terminus (GATA1s)." (PMID 35838049, 2022).
Diamond-Blackfan anemia (17 papers, 2013 to 2025). A congenital aregenerative and often macrocytic anemia with erythroblastopenia. "In line with the crucial role of GATA1 in physiological hematopoiesis, germline GATA1 mutations are associated with hereditary thrombocytopenia, dyserythropoietic anemia, and Diamond-Blackfan anemia." (PMID 33777792, 2021). "Mutations involving exon 2 donor splice site of GATA1 gene have recently been reported in patients with clinical features consistent with the current diagnostic criteria for Diamond Blackfan anemia (DBA) or with DBA like features." (PMID 26445707, 2015). "As an additional example we examined a splice-site variant in the GATA1 gene was that recently shown to cause Diamond-Blackfan anemia (DBA, OMIM #105650)." (PMID 24268183, 2013). "Exonic/intronic GATA1 mutations causes Diamond-Blackfan Anemia (DBA)-like disease." (PMID 36845397, 2023). "In addition, a few cases with Diamond-Blackfan anemia (DBA)-like phenotype have germline mutations in GATA1, which also lead to exclusive expression of GATA1s12–14." (PMID 36447001, 2022). "GATA1 variants cause a range of hematological phenotypes, including X-linked thrombocytopenia with or without dyserythropoietic anemia, with several different syndromic manifestations including Diamond Blackfan Anemia, β-thalassemia and congenital erythropoietic porphyria." (PMID 37377909, 2023). "These preclinical safety and efficacy data provide strong support for the first-in-human universal gene therapy trial for Diamond-Blackfan anemia through regulated GATA1 expression." (PMID 39532107, 2025). "These pre-clinical efficacy and safety data provide support to initiate what will be the first-in-human gene therapy trial of regulated GATA1 expression as a universal treatment for Diamond-Blackfan anemia." (PMID 39532107, 2025). "Most patients with Diamond Blackfan anemia harbor mutations in genes coding for ribosomal subunits, the most common being RPS19, that lead to a selective impaired production of full-length GATA1 and GATA1-Short23,50,51." (PMID 31628330, 2019). "GATA1 protein synthesis is reduced in Diamond-Blackfan anemia (DBA), a congenital red cell aplasia caused by reduced biosynthesis of ribosomes, and mutations in GATA1 can cause a DBA-like phenotype." (PMID 30087616, 2018). "By applying EMSA and ChIP methodologies in mouse erythroleukemia cells we show that GATA1 and PU.1 bind in vitro and in vivo the proximal promoter region of the RPS19 gene which is frequently mutated in Diamond-Blackfan Anemia." (PMID 26447946, 2015). "Diamond-Blackfan anemia (DBA) is a hypoplastic anemia characterized by the impaired production of RBCs, and some of the pathogenic mutations were mapped to a splice site of the GATA1 gene, causing the impairment of full-length protein production." (PMID 37296674, 2023). "Indeed, erythroid-specific GATA1 enhancers can drive restricted expression of GATA1 to rescue erythroid differentiation in Diamond-Blackfan anemia." (PMID 37595278, 2023). "Our observed phenotype of increased megakaryopoiesis due to forced expression of GATA1-Short seems to be at odds with a subset of Diamond Blackfan anemia patients, which is a genetic disease that usually presents in infancy and is characterized by low red blood cell counts." (PMID 31628330, 2019).